MALAT1 (metastasis associated lung adenocarcinoma transcript 1)
Diseases named in the same sentence as MALAT1 in open-access papers (continued):
Sharing a sentence is not in itself a finding about the gene and the disease.
ischemia (12 papers, 2016 to 2025). A hypoperfusion of the BLOOD through an organ or tissue caused by a PATHOLOGIC CONSTRICTION or obstruction of its BLOOD VESSELS, or an absence of BLOOD CIRCULATION. "In the present study, we utilized the Malat1-deficient mice model to explore the effects and molecular mechanisms of Malat1 on hindlimb ischemia-induced angiogenesis." (PMID 29891768, 2018). "A recent investigation has confirmed that lncRNA MALAT1 promotes myocardial cell apoptosis by regulating miR-145/Bnip3 axis, thereby contributing to ischemia/reperfusion myocardial injury." (PMID 41170388, 2025). "This is consistent with previous reports by us and others showing that Malat1 is a crucial regulator of endothelial cell proliferation and migration and is required for ischemia-induced neovascularization in the hind limb." (PMID 36883566, 2023). "MALAT1-mediated inhibition of apoptosis plays an important role in the cognitive improvement by exercise in ischemia/reperfusion injury." (PMID 34123418, 2021). "Specifically, MALAT1 acts as an endogenous sponge to adsorb miR-200a-3p and downregulate the level of miR-200a-3p, thus promoting the inflammatory damage of cardiomyocytes during ischemia/reperfusion injury." (PMID 41170388, 2025). "However, other lncRNAs, such as Meg3, Malat1, GAS5, NEAT1, and LOC105374325 mediated the renal cell apoptosis caused by ischemia." (PMID 36552750, 2022). "Moreover, Malat1 was highly enriched in hypoxic kidneys of mice following induction of I/R-injury (30 minutes of ischemia, 24 h of reperfusion)." (PMID 29467431, 2018).
Alzheimer disease (11 papers, 2018 to 2025). A progressive, neurodegenerative disease characterized by loss of function and death of nerve cells in several areas of the brain leading to loss of cognitive function such as memory and language. "The upregulation of lncRNA MALAT1 expression has been associated with the suppression of neuronal death and neuroinflammation in patients diagnosed with Alzheimer's Disease (AD)." (PMID 38577023, 2024). "Recently, an increasing number of studies have also linked MALAT1 to neurological disorders such as schizophrenia (SZ), Alzheimer’s disease (AD) and neuropathic pain." (PMID 38281050, 2024). "In the context of an Alzheimer's disease (AD) model with overexpression of MALAT1, it was shown that the expression of miR-125b was downregulated." (PMID 38577023, 2024). "Additionally, in the context of Alzheimer’s disease (AD) neuroinflammation, lncRNA MALAT1 downregulates the expression of IL-6 and TNF-α while concurrently enhancing IL-10 levels, suggesting the potential therapeutic value of targeting lncRNA MALAT1 in AD." (PMID 39827195, 2025). "To verify whether NEAT1, HOTAIR, and MALAT1 expression is also altered in Alzheimer’s disease, we quantified their levels by qRT-PCR in the temporal cortex, hippocampus, and cerebellum of the same AD patients and age-matched healthy controls which were analyzed in our previous work." (PMID 29997370, 2018). "A previous study reported that icariin (ICA) alleviated Alzheimer’s disease pathology by regulating the expression of MEG3 and MALAT1 lncRNAs and modulating the AKT/GSK3β signaling pathway." (PMID 40869265, 2025). "In Alzheimer’s Disease models based on NGF-stimulated PC12 cells and primary cerebral cortex neurons, MALAT1 inhibits neuron apoptosis and neuroinflammation, while it stimulates neurite outgrowth via miR-125b-regulated PGTS2, CKD5, and FOXA1 expression." (PMID 33192306, 2020).
autoimmune disease (11 papers, 2018 to 2025). A disorder resulting from loss of function or tissue destruction of an organ or multiple organs, arising from humoral or cellular immune responses of the individual to their own tissue constituents. "LncRNA MALAT1 (metastasis-associated lung adenocarcinoma transcript-1) had been shown to play a role in the development of autoimmune diseases." (PMID 31736958, 2019). "Therapeutically, MALAT1 lncRNA is a novel tolerance regulator with important implications in settings involving DCs, such as transplantation, autoimmune diseases, cancer, and pathogenic infection." (PMID 30150986, 2018). "MALAT1 is a large (6.5 kb), nuclear-enriched, and highly conserved lncRNA, which has important regulatory functions related to inflammation and is associated with autoimmune diseases." (PMID 38622662, 2024). "MALAT1 was expressed on chromosome 11q13, and widely expressed in multiple normal tissues such as reproductive, endocrine and immune systems with an important role in autoimmune diseases including RA, SLE, MS." (PMID 31736958, 2019). "Therefore, overexpressed MALAT1 induces tDCs and immune tolerance in transplantation and autoimmune disease by the miR155/DC-SIGH/IL10 axis." (PMID 30150986, 2018). "Therefore, overexpressed MALAT1 induces tDCs and immune tolerance in heart transplantation and autoimmune disease by the miRNA-155/DC-SIGH/IL10 axis." (PMID 30150986, 2018). "In this study, we first identified the lncRNA MALAT1 in tolerized cardiac allografts and further elucidated the contribution of MALAT1 to the tolerogenic function of DCs and immune tolerance induction in heart transplantation and autoimmune disease." (PMID 30150986, 2018). "Notable representation is also observed in psoriasis and autoimmune diseases, particularly through lncRNAs such as TINCR, MALAT1, and NORAD, as well as miRNAs like miR-17-5p, miR-26b-5p, and let-7i-5p." (PMID 40725409, 2025). "In addition to its role in transplantation, the transfer of MALAT1 enforced the protection of DCs from the development of EAM in mice, further proving its immune-tolerant effect in autoimmune disease." (PMID 30150986, 2018).
head and neck squamous cell carcinoma (11 papers, 2018 to 2025). A squamous cell carcinoma that arises from any of the following anatomic sites: lip and oral cavity, nasal cavity, paranasal sinuses, pharynx, larynx, and salivary glands. "Metastasis-associated lung adenocarcinoma transcript 1 (MALAT1), a well-known lncRNA, has been reported to play crucial roles in multiple malignancies including head and neck squamous cell carcinoma (HNSCC)." (PMID 36813772, 2023). "Coincidentally, Wang’s recent study demonstrated that STAT3 activated the MALAT1 transcriptionally activation by binding to the MALAT1 promoter region in human head and neck squamous cell carcinoma." (PMID 30591689, 2018). "Another study pointed out that MALAT1 was overexpressed in head and neck squamous cell carcinoma (HNSCC) cells." (PMID 36829256, 2023). "Although research on lncRNAs for head and neck squamous cell carcinoma is limited, a recent study has reported few differentially expressed lncRNAs such as HOTAIR, NEAT1, UCA1, and MALAT1, in oral cancers." (PMID 30002503, 2018). "Upregulated TGF-β in head and neck squamous cell carcinoma (HNSCC) may promote STAT3 activation, which binds to the MALAT1 promoter and activates its expression, thereby inducing EMT and accelerating HNSCC metastasis." (PMID 35006436, 2020).
liver diseases (11 papers, 2017 to 2025). "A deeper understanding of the functions of MALAT1 and its interaction network will lay the foundation for the development of lncRNAs as therapeutic targets and as diagnostic or prognostic biomarkers for liver diseases." (PMID 35145971, 2021). "Interestingly, various lncRNAs, such as H19, HOTAIR, and MALAT-1, and their association with liver diseases have been highlighted as potential markers for disease progression or prognosis." (PMID 32157157, 2020). "Deregulation of H19 and MALAT1 has been associated with liver disease." (PMID 30515189, 2018). "Although this study focused on NAFLD, it demonstrates the potential of targeting the lncRNA MALAT1 in the treatment of liver disease, which also provides a potential therapeutic strategy for future applications in ALD." (PMID 40130250, 2025). "Plasma MALAT1 was up-regulated in HCC compared to hepatic diseases (chronic viral hepatitis and NAFLD/NASH), and it can be used to distinguish HCC from other liver diseases." (PMID 33477833, 2021). "In the current review, we summarize the latest literature about the function roles of MALAT1 in liver disorders." (PMID 35145971, 2021). "Probing the regulatory mechanism and cross talk of MALAT1 with other signaling pathways of pathological processes would improve the prognosis, diagnosis of liver diseases, and offer a promising candidate target for therapeutic interventions." (PMID 35145971, 2021). "Circulating levels of MALAT1 were elevated in HCC samples (9.17 ± 43.62) compared to individuals with hepatic disease (1.10 ± 0.82) and healthy controls (0.85 ± 1.10)." (PMID 30159431, 2017). "The authors collected plasma samples from preoperative HCC patients (n = 88), hepatic disease patients (n = 28), and healthy controls (n = 51) and measured plasma MALAT1 using qRT-PCR." (PMID 28835896, 2017). "The expression levels of MALAT1 were significantly higher in HCC patients than in hepatic disease patients." (PMID 28835896, 2017). "The levels of serum HULC, MALAT1, Linc00152, PTTG3P, SPRY4-IT1, UBE2CP3, and UCA1 were significantly higher in HCC patients than in patients with benign liver diseases and healthy controls, whereas serum PTENP1 was significantly decreased in HCC patients compared with healthy participants." (PMID 32733618, 2020).
lung squamous cell carcinoma (11 papers, 2014 to 2024). "There has been an association between SNP rs3200401 in lncRNA MALAT1 and susceptibility of lung squamous cell carcinoma and NSCLC, via altered MALAT1’s structural properties and downstream genes contributing to the formation and progression of cancer." (PMID 37888204, 2023). "It was found that the high expression of MALAT-1 in squamous cell lung carcinoma was closely related to the poor prognosis of cases." (PMID 34858541, 2021).
multiple sclerosis (11 papers, 2019 to 2025). A progressive autoimmune disorder affecting the central nervous system resulting in demyelination. "Previous study showed that the rs619586-A and rs3200401-T haplotype of MALAT1 is associated with a higher risk of multiple sclerosis (MS), providing additional evidence for the role of MALAT1 in MS pathogenesis." (PMID 36934373, 2023). "Firstly, the contribution of MALAT1 to neuroinflammation in CNS tissues from multiple sclerosis (MS) patients was verified." (PMID 39798064, 2025). "The contribution of Malat1 lncRNA to autoimmune neuroinflammation has been observed in patients with multiple sclerosis and mice with encephalomyelitis." (PMID 35309141, 2022). "Downregulation of MALAT1 promotes the polarization of macrophages to M1 phenotype and induces the proliferation of T cells in multiple sclerosis (MS), indicating the potential anti-inflammatory effect of MALAT1 on MS." (PMID 34527672, 2021). "The decision tree revealed that if MALAT1 less than or equal to 1, then it is 75% likely of ‘No Multiple Sclerosis’." (PMID 30514825, 2019).
osteoarthritis (11 papers, 2019 to 2024). A noninflammatory degenerative joint disease occurring chiefly in older persons, characterized by degeneration of the articular cartilage, hypertrophy of bone at the margins and changes in the synovial membrane. "Metastasis Associated Lung Adenocarcinoma Transcript-1 (MALAT1) is implicated in regulating the inflammatory response and in the pathology of several chronic inflammatory diseases, including osteoarthritis (OA)." (PMID 33916321, 2021). "Another group reported that miR-124–3p impaired MALAT1 stability and led to suppression of chondrocyte pytoptosis and inhibition of cartilage injury in osteoarthritis." (PMID 37779916, 2023). "Resveratrol was reported to regulate the lncRNA MALAT1 and miR-9/NF-κB axis and retard osteoarthritis progression." (PMID 37779916, 2023). "One group validated the expression and function of MALAT1 in osteoblasts from osteoarthritis patients." (PMID 37779916, 2023). "MALAT1 from MSCs-derived extracellular vesicles blocked cartilage degradation and attenuated inflammation in osteoarthritis." (PMID 37779916, 2023). "For example, in osteoarthritis, MALAT1 promotes inflammatory progression and extracellular matrix degradation by regulating the miR-150-5p/AKT3 axis." (PMID 38114929, 2023). "MALAT1 was found to regulate the inflammatory synovial fibroblast phenotype in obese patients with osteoarthritis." (PMID 37779916, 2023). "MALAT1 is upregulated in osteoarthritis and facilitates cartilage ECM degradation in IL-1β-induced chondrocytes." (PMID 35626352, 2022). "In contrast, in cartilage tissues collected from healthy and osteoarthritis patients, MALAT1 was shown to be significantly upregulated." (PMID 32791451, 2020). "Altogether, MALAT1 controls osteoarthritis development and progression." (PMID 37779916, 2023). "Thus, MALAT1 is responsible for cartilage cells apoptosis, extracellular matrix degradation, and osteoarthritis development via the miR-150-5p/AKT3 axis." (PMID 32791451, 2020). "Liu and coworkers observed that MALAT1 sponged miR-145 and elevated ADAMTS5, resulting in regulation of IL-β-mediated viability and cartilage matrix degradation in osteoarthritis." (PMID 37779916, 2023).
rheumatoid arthritis (11 papers, 2019 to 2026). A chronic, systemic autoimmune disorder characterized by inflammation in the synovial membranes and articular surfaces. "As an example, the expression levels of MALAT1 and miR-1-3p were significantly higher in newly diagnosed patients with rheumatoid arthritis than NC." (PMID 38622662, 2024). "The lncRNAs HOTAIR, lincRNA‐p21, lncRNA H19 and MALAT1 play important roles in the clinical diagnosis and progression of rheumatoid arthritis (RA)." (PMID 36607351, 2023). "In accordance with that, the MALAT1 level was decreased in serum exosomes and FLSs from patients with rheumatoid arthritis." (PMID 35796900, 2022). "This study aimed to evaluate the association of four lncRNAs (ANRIL, lnc-DC, MALAT1, ZFAS1) genes single nucleotide polymorphisms (SNPs) with susceptibility to rheumatoid arthritis (RA) patients, as well as their expression levels." (PMID 31736958, 2019). "Similarly, both NEAT1 and MALAT1 have been suggested as clinical outcome biomarkers in rheumatoid arthritis." (PMID 39337694, 2024). "The authors report on a study that evaluated the association of four long noncoding RNA (lncRNA) (ANRIL, lnc-DC, MALAT1, ZFAS1) gene single-nucleotide polymorphisms (SNPs) with susceptibility to rheumatoid arthritis (RA) patients, as well as their expression levels." (PMID 34956240, 2021).
acute myeloid leukemia (10 papers, 2019 to 2025). Acute myeloid leukemia (AML) is a group of neoplasms arising from precursor cells committed to the myeloid cell-line differentiation. "For example, in acute myeloid leukemia, MALAT1 regulates cells migration, proliferation and apoptosis, by releasing CXCR4 from the regulatory inhibition of hsa-miR-146." (PMID 35008626, 2021). "Overexpression of MALAT1 was investigated in acute myeloid leukemia (AML) patients and AML cell lines, and was found to promote cancer progression via mA RNA modification of ZEB1 gene." (PMID 37266436, 2023).
injury (10 papers, 2018 to 2023). Damage inflicted on the body as the direct or indirect result of an external force, with or without disruption of structural continuity. "In an LPS-induced acute lung injury rat model, researchers found that MALAT1 knockdown plays protective roles by upregulating miR-146a." (PMID 31871512, 2019). "Besides, previous studies have confirmed that MALAT1 targeting miR-370-3p attenuates LPS-induced acute renal injury." (PMID 36793374, 2023). "Furthermore, knockdown of MALAT1 was reported to suppress inflammatory response in LPS-induced acute lung injury and kidney injury." (PMID 33134293, 2020).
retinoblastoma (10 papers, 2018 to 2025). A malignant tumor that originates in the nuclear layer of the retina. "(iii) Considering the impairment of autophagy as a potential cause of pterygiums, we observed that MALAT1, a long non-coding RNA that promotes autophagy in retinoblastoma cells, was markedly downregulated in the European pterygiums." (PMID 38732006, 2024). "Long noncoding RNA (lncRNA) metastasis-associated lung adenocarcinoma transcript 1 (MALAT1) was reported as an oncogene in many tumors including retinoblastoma (RB)." (PMID 34222668, 2021). "In retinoblastoma, miR-124 participates in a regulatory network with lncRNAs Malat1 and XIST, which both function as oncogenes by enhancing growth and metastasis through downregulation of miR-124." (PMID 31616462, 2019). "MALAT1 modulates the autophagy of retinoblastoma cell through miR-124-targated stx17." (PMID 31992960, 2020). "Finally, in retinoblastoma, Malat1 downregulated miR-124 activity, leading to activation of the transcription factor SLUG, which is also targeted by miR-124." (PMID 31616462, 2019). "Additionally, the study confirmed the reciprocal regulation between MALAT1 and miR-124, and demonstrated that Syntaxin17 (a soluble NSF attachment protein receptor of the autophagosome) directly binds to miR-124 to regulate autophagy in retinoblastoma cells." (PMID 40128064, 2025).
clear cell kidney carcinoma (9 papers, 2015 to 2025). "Here, we found that MALAT1 exist a higher fold change (Tumor/Normal) in clear cell kidney carcinoma (KIRC) from The Cancer Genome Atlas (TCGA) Data Portal and a negative correlation with miR-200s family." (PMID 26461224, 2015). "Real-time PCR analysis demonstrated that MALAT1 was ubiquitously expressed at higher levels in a panel of 5 human clear cell renal cell carcinoma lines than immortalized human proximal renal tubule epithelial cell line HK-2." (PMID 26461224, 2015). "Another study indicated that lower expression of miR‐194‐5p and higher expression of MALAT1, ACVR2B were related with advanced TNM stage, larger tumour size (≥4 cm) and poor prognosis of patients with clear cell kidney carcinoma." (PMID 33484504, 2021). "ACVR2B has also been reported to be a member of the MALAT1/miR-194-5p/ACVR2B signaling axis, which promotes clear cell kidney carcinoma (KIRC) progression." (PMID 31886217, 2019).
metastatic carcinoma (9 papers, 2014 to 2025). A carcinoma which has spread from the original site of growth to another anatomic site. "Metastasis-associated lung adenocarcinoma transcript 1 (MALAT1), originally discovered in metastatic carcinoma cells, has been implicated in HIV transcription." (PMID 38891030, 2024). "In a murine metastatic cancer model, loss of MALAT1 resulted in differentiation of primary tumours and a significant reduction in metastasis." (PMID 36841868, 2023). "Studies including patient cohorts exhibiting a metastatic cancer phenotype have noted increased levels of MALAT1 in high-risk metastatic tumors compared to low risk tumors." (PMID 25101115, 2014). "Early studies consistently report that MALAT1 is up-regulated in human cancer tissues of various organ origins, particularly metastatic cancer tissues, and that high levels of MALAT1 in cancer tissues are associated with poor patient outcome." (PMID 32174966, 2020). "Though the precise function of MALAT1 is still unclear, it has been shown to be involved in a variety of metastatic cancers." (PMID 26407100, 2015). "Collectively, these results indicate that MALAT1 may have an important role in metastatic cancer." (PMID 25101115, 2014). "Furthermore, the results showed statistically significant increases in MALAT1 expression in patients with metastatic cancer with lymph node involvement compared to non‐metastatic cancer." (PMID 40231344, 2025).